BDNF (brain derived neurotrophic factor)
Diseases named in the same sentence as BDNF in open-access papers (continued):
Sharing a sentence is not in itself a finding about the gene and the disease.
glaucoma (continued). "There is also substantial evidence that depletion of BDNF plays a central role in the onset of glaucoma, with evidence for impaired retrograde BDNF transport found in experimental models of ocular dysfunction." (PMID 29853847, 2018). "Tropomyosin-related receptor kinase-B (TrkB) downregulation has been reported in many neurological diseases including glaucoma, potentially limiting the effect of sustained or repeated BDNF delivery." (PMID 30258047, 2018). "Other pathologies related to decreased BDNF/TrkB signalling are neurodegenerative diseases of the retina such as glaucoma, age-related macular degeneration, diabetic retinopathy or retinitis pigmentosa." (PMID 28134845, 2017). "We found recently that a modest increase of retinal BDNF protects some RGC subtypes in a mouse model of experimental glaucoma." (PMID 28101532, 2017). "Recently, we showed that BDNF topical eye treatment in the form of collyrium was able to increase the retinal level of BDNF up to rescue visual responses in a murine model of glaucoma." (PMID 28289378, 2017). "BDNF expression in the group where the extract was injected on the 2nd day after glaucoma induction was lower than in healthy eyes, but slightly higher than in the glaucoma control eyes." (PMID 29109409, 2017). "Upregulation of BDNF in glaucoma is likely to result from retinorecipient targets responding to glaucoma-relevant stress to improve RGC survival." (PMID 28223915, 2017). "In the optic nerve head (ONH), which is a major site of stress in glaucoma, levels of BDNF appeared similar in saline- and microbead-injected eyes from vehicle treated rats." (PMID 28223915, 2017). "The protective effect of neurotrophic factors such as brain derived neurotrophic factor (BDNF) makes them promising therapeutic candidates for neurodegenerative diseases including glaucoma." (PMID 28101532, 2017). "Virally mediated gene expression of BDNF in the retina promotes robust RGC survival in various experimental glaucoma models, including optic nerve transection, high IOP and intravitreal injection of NMDA." (PMID 27657046, 2016). "Thereto, the validated rAAV2/1-CMV-BDNF vector was used to upregulate BDNF in the mouse SC in an attempt to induce long-distance neurotrophic protective effects on the RGCs in both models of experimental glaucoma." (PMID 26560713, 2015). "The main objective of the performed experiments was to study the contribution of BDNF, the most commonly studied neurotrophin, to glaucoma disease progression, using two experimental mouse glaucoma models, commonly applied to mimic glaucoma pathology." (PMID 26560713, 2015). "Overall, retinal and collicular BDNF and TrkB levels were differentially altered after experimentally induced glaucoma in the ONC and OHT models." (PMID 26560713, 2015). "The current study, investigating levels of BDNF together with its main receptor TrkB in the retina and SC in two mouse models of experimentally induced glaucoma, firstly demonstrated that retinal BDNF levels were elevated after ONC." (PMID 26560713, 2015). "The observed differences in endogenous expression of BDNF and TrkB within the 2 glaucoma models then indeed hint to a (partial) preservation of axonal transport in the OHT model as compared to ONC at the included time points." (PMID 26560713, 2015). "Defining a specific role for BDNF signaling within glaucoma pathology remains difficult, as various studies, using a number of animal glaucoma models, have culminated in a variety of unique results, the present work included." (PMID 26560713, 2015). "In rodent experimental models of glaucoma with elevated IOP the retinal levels of either BDNF or its receptor were unaffected." (PMID 25536045, 2014). "Astrocytes are known to influence RGC health in glaucoma through increased reactivity that leads to production of both neuroprotective and neurodestructive factors, including brain-derived neurotrophic factor, tumor necrosis factor alpha and nitric oxide." (PMID 25133067, 2014).
glaucoma (continued). "Here, we investigated the effectiveness of BDNF treatment to preserve vision in a glaucoma experimental model." (PMID 25536045, 2014). "In rat, application of exogenous BDNF to the retina through intravitreal injection resulted in a promotion of RGC survival thus there is extensive interest in delivering exogenous BDNF to the retina as a glaucoma therapy." (PMID 25426041, 2014). "It is interesting to note that brimonidine, which can potentially upregulate BDNF, preserved optic nerve axons in a hypertensive rat glaucoma model." (PMID 23316132, 2012). "Specifically, delivery of brain derived neurotrophic factor (BDNF) had a protective effect in animal models of glaucoma." (PMID 17183666, 2006). "Additionally, IPA® predicted elevated activation of brain-derived neurotrophic factor (BDNF), widely considered a neuroprotective protein and the focus of gene therapy for glaucoma." (PMID 40076480, 2025). "Sharif advocates for “vertical” therapeutic strategies that simultaneously target aqueous humor dynamics (e.g., via EP2 agonists like omidenepag isopropyl) and RGC survival pathways (e.g., BDNF gene therapy), addressing both the upstream and downstream pathology in glaucoma." (PMID 40573278, 2025). "In addition, molecular biology analyses showed that Epicolin significantly upregulated the neurotrophic factor BDNF, which is known for its neuroprotective effect and is significantly reduced in glaucoma." (PMID 39861721, 2025). "Abnormalities in BDNF signaling have been observed across multiple models of retinal diseases, including glaucoma, and there is accumulating evidence that diminished BDNF and TrkB signaling may also play a role in the pathology of human glaucoma." (PMID 40002456, 2025). "This study provides compelling preclinical evidence that dual gene therapy combining TrkB and BDNF expression may offer an effective neuroprotective strategy for glaucoma." (PMID 40838110, 2025). "Negative association of Shp2 on BDNF/TrkB signaling is effectively dependent on the Cav-1 protein and provides an in vivo protective effect under experimental glaucoma conditions." (PMID 37962455, 2024). "We also more precisely evidenced that the negative association of Shp2 phosphatase and BDNF/TrkB signaling provides an in vivo protective effect under chronic experimental glaucoma conditions and it is effectively dependent on the Cav-1 protein." (PMID 37962455, 2024). "Indeed, BDNF is of interest for treating neurodegenerative diseases such as glaucoma and is reduced in glaucomatous eyes." (PMID 38742929, 2024). "BDNF induces Shp2 phosphorylation and its subsequent association with adaptor proteins GRB2/SOS for complete MAPK activation which is shown to be neuroprotective in glaucoma conditions." (PMID 37962455, 2024). "Notably, retinal BDNF levels were observed to increase in a pressure-induced animal model of glaucoma." (PMID 38562304, 2024). "In addition, neurotrophic factors (NTFs), in particular brain-derived neurotrophic factor (BDNF), have been identified in the pathogenesis of glaucoma." (PMID 38818519, 2024). "Recent studies have revealed that increased TrkB signaling in RGCs could be an effective therapy for glaucoma, but maintaining a continued supply of BDNF is impractical." (PMID 36463402, 2023). "BDNF-TrkB signaling plays key physiological roles in the protection of neurons, including RGCs, and decreased expression levels of BDNF and TrkB are observed in the optic nerve head tissues from glaucoma patients." (PMID 36463402, 2023). "The registration of TF denaturation profiles in POAG suspects can be complemented by the analysis of TF biomarkers of the other forms of the disease, such as normal tension glaucoma (BDNF) and primary angle-closure glaucoma (mucin 5AC), thereby enabling their differential diagnosis." (PMID 37108298, 2023). "Elevated IOP and the resulting mechanical strain on the optic nerve head may hinder the retrograde transport of BDNF in glaucoma." (PMID 38132117, 2023).
glaucoma (continued). "In glaucomatous eyes, BDNF expression was observed to be significantly lower in aqueous humor, lacrimal fluid, and serum relative to the healthy subjects, suggesting a possible correlation between low BDNF levels and the early stages of glaucoma." (PMID 35668928, 2022). "The treatment with S1R agonists can increase BDNF levels and might provide benefit in diseases such as glaucoma." (PMID 35269763, 2022). "Regarding neuroprotection, studies have shown that exercise protected against glaucoma through brain-derived neurotrophic factor (BDNF) signalling, which showed that BDNF levels were significantly reduced in the injured retinas of non-exercised mice but maintained in exercised mice." (PMID 36012964, 2022). "Several NTFs have been reported to be associated with glaucoma, including nerve growth factor (NGF), brain-derived neurotrophic factor (BDNF), ciliary neurotrophic factor (CNTF), fibroblast growth factor 2 (bFGF), glial-derived neurotrophic factor (GDNF), and neurturin." (PMID 36579616, 2022). "It is also argued that interrupted retrograde BDNF delivery can not be considered as the only cause of RGC death in glaucoma." (PMID 35668928, 2022). "Increasing evidence of reduced BDNF and TrkB signaling in human glaucoma has also been suggested." (PMID 33920974, 2021). "Our results also suggest that dendrite formation and the related BDNF involvement could serve as novel treatment targets for glaucoma, especially for NTG, regarding the neuronal functions of hsa-miR-375." (PMID 34561506, 2021). "Thus, BDNF was significantly lower in glaucoma patients (0.7-fold) when compared with controls, with an opposite trend to that observed by the same authors in tear film." (PMID 34439995, 2021). "Considering the direct regulation of hsa-miR-375 effect on the BDNF gene, the results of our study may also support the BDNF gene as a potential target for glaucoma gene therapy, especially for NTG." (PMID 34561506, 2021). "As BDNF may trigger a wide variety of neutroprotective mechanisms, we may hypothesize that BDNF may benefit the glaucoma course by acting as anti-apoptotic, as well as anti-autophagic molecule, to strengthen cell survival." (PMID 32967086, 2020). "The microbead occlusion model of glaucoma, which proved its reproducibility in our hands and was recently used in a non-human primate with a visual system similar to our own, represents an attractive model for determining the impact of BDNF interventions on TrkB responses to glaucoma." (PMID 32872441, 2020). "The protective effects of niacin against glaucoma may be due to its ability to upregulate brain-derived neurotrophic factor (BDNF), and improve vascular endothelial function by decreasing vascular oxidative stress." (PMID 32214001, 2020). "The importance of BDNF overexpression for the protection of RGCs from degeneration in the central part of the glaucomatous retina has been confirmed by the significant interaction of glaucoma with BDNF overexpression (p = 0.0005)." (PMID 32872441, 2020). "Next, we performed ELISA to answer the question of whether at six weeks after the induction of glaucoma BDNF protein concentrations in the retina are reduced, and if so, whether a deficit also develops in the contralateral eye." (PMID 32872441, 2020). "Furthermore, we found that the expression levels of BDNF and TrkB are reduced in the optic nerve head and retina in glaucomatous marmosets, consistent with the data gathered from observation of human glaucoma patients." (PMID 31619716, 2019). "These initial findings regarding the capability of BDNF to induce beneficial synaptic changes may aid in the development of neuroenhancement techniques that can be used to treat synaptic dysfunction in glaucoma." (PMID 31142572, 2019).
glaucoma (continued). "Nevertheless, most of this research has focused on the involvement of BDNF–TrkB signaling in tension glaucoma, primary open angle glaucoma, and diabetic retinopathy, but the alterations in both proBDNF and mBDNF expression levels and patterns during the development of AMD are barely known." (PMID 30871541, 2019). "However, there are only a few studies that have investigated the CaMKII and CREB pathway in relation to synaptic changes in RGCs and its modulation by BDNF in glaucoma." (PMID 31142572, 2019). "However, a recent study utilizing topical eye application of BDNF eye-drops on mice showed a similar protective result in animals with experimental glaucoma." (PMID 29896439, 2018). "Interestingly, an acute elevation of intraocular pressure in experimental glaucoma leads to an obstruction of BDNF retrograde axonal transport from central target cells to the RGC soma and accumulation of TrkB in the optic nerve head." (PMID 28134845, 2017). "Several studies have shown that BDNF transiently delays RGC death in glaucoma." (PMID 28134845, 2017). "A series of studies has suggested that BDNF protects RGCs in experimental glaucoma." (PMID 28101532, 2017). "Thus, the reported results make BDNF a good candidate to drive full neuroprotective and repair strategies in neurodegenerative diseases, including glaucoma and AD." (PMID 28289378, 2017). "Consistently, BDNF is reduced in the optic nerve head of glaucoma patients." (PMID 27657046, 2016). "Therefore, retinal BDNF measurements were repeated in animals, in which viral vector injection was combined with experimentally induced glaucoma." (PMID 26560713, 2015). "We observed a decrease of BDNF expression level with the advancement of glaucoma." (PMID 25893192, 2015). "In our study, we examine the relationship between single nucleotide polymorphisms (SNPs) of APOE (rs449647), BDNF (rs2030324), GRIN2B (rs3764028), and HSP70-1 (rs1043618) genes and the possible occurrence risk of primary open angle glaucoma in the Polish population." (PMID 25893192, 2015). "Thus, despite a clear BDNF upregulation in the SC, the viral vector-mediated brain treatment did not exert neuroprotective effects on RGCs in the present experimental glaucoma models." (PMID 26560713, 2015). "Interestingly, supplying BDNF by intravitreal injection results in a partial protective effect in animal model of glaucoma." (PMID 25536045, 2014). "A reduction in BDNF is thought to contribute to the complex mechanisms of RGC death in glaucoma." (PMID 25426041, 2014). "Overexpression of BDNF delays RGC death in experimental glaucoma." (PMID 21150032, 2011). "The molecular mechanisms of RGC death followed by axonal degeneration in glaucoma are not fully understood, but one generally accepted possibility is that apoptotic signaling is triggered under conditions of impaired trophic support due to a blockade of retrograde axonal transport of BDNF/TrkB90,91." (PMID 40596696, 2025). "It is possible that the microbiome could aid in glaucoma management via modulation of BDNF levels." (PMID 38937293, 2024). "However, retinal ganglion cell dendrites are plastic, allowing for the reintegration of neuronal circuits (e.g. via BDNF or insulin treatment), and as such, dendritic recovery may provide a useful substrate for visual recovery in glaucoma." (PMID 39180087, 2024). "In glaucoma, reactive microglial cells initially phagocytize the debris of damaged or dead RGCs, contributing to the maintenance of a toxin-free microenvironment, and also release neurotrophic factors such as BDNF or CNTF, providing neuroprotection and promoting tissue neuroregeneration." (PMID 38333055, 2024). "More interestingly, growth factors (GFs) and neurotrophic factors (NFs) including platelet-derived growth factor (PDGF) and BDNF are proposed as main ingredients for the paracrine effects of hypoxia-cultivated stem cells and are known to promote nerve survival and control synapses in glaucoma eyes." (PMID 37175778, 2023).
glaucoma (continued). "Interestingly, in a case-control study, serum BDNF and NGF levels were low in patients with early and moderate glaucoma, indicating that the NTFs have a potential to serve as diagnostic biomarkers for glaucoma." (PMID 35668928, 2022). "However, another study in a rat glaucoma model showed that moderate overexpression of BDNF restored normal TrkB levels and did not cause downregulation." (PMID 36361771, 2022). "The authors concluded that these findings concerning the ability of BDNF to encourage useful synaptic changes may assist in the development of neuroenhancement approaches for the treatment of disturbed synaptic function in glaucoma." (PMID 34561506, 2021). "Therefore, BDNF’s well established neuroprotective role, increasing evidence for neuroprotection in RGCs, and its potential pathophysiological role in human glaucoma most likely explain the higher proportion of papers exploring novel gene therapy approaches with BDNF." (PMID 33920974, 2021). "Diminished level of BDNF in depression may affect the survival of RGC in glaucoma development." (PMID 33723349, 2021). "Endogenous BDNF could be stimulated after glaucoma induction." (PMID 31142572, 2019). "Thus, BDNF non-invasive treatments represent a promising feasible therapeutic strategy to preserve neuronal function and diminish cell vulnerability in neurodegenerative diseases such as the AD and glaucoma." (PMID 28289378, 2017). "Different approaches have been used to manipulate BDNF levels, such as intravitreal injection of BNDF protein, infection with adeno-associated virus expressing BDNF for gene therapy, and transplantation of stem cells in animal models of experimental glaucoma or optic neuropathy." (PMID 28101532, 2017). "Crucially, this BDNF protective effect can also be observed following delayed application of BDNF, a significant new observation that may have important implications for the treatment of neurodegenerative disorders, such as glaucoma." (PMID 27285957, 2016). "Interestingly, the BDNF levels in the serum of primary open-angle glaucoma patients and the tears of normal tension glaucoma patients are significantly lower than control subjects, suggesting that BDNF may be a biomarker for glaucoma." (PMID 27657046, 2016). "Although lower BDNF level in glaucoma could be related to extraocular reasons such as, for example, more sedentary lifestyle of glaucoma patients (exercise may increase serum and plasma BDNF level, these data correspond to the concept of BDNF insufficiency in glaucoma." (PMID 27092075, 2016). "It has to be proved whether protracted treatment with BDNF instead of short treatment as reported here will be feasible for the rodent and, possibly, human retina to prevent RG cell death and optic nerve atrophy in glaucoma." (PMID 25536045, 2014). "Studies in experimental glaucoma have indicated that the retrograde transport of BDNF may be compromised following the experimental elevation of intraocular pressure but this does not necessarily imply a direct link between a reduction in BDNF levels and the reduction in dendritic integrity." (PMID 23977271, 2013). "Thus, BDNF may have beneficial effects on not only on RGC bodies but also on their axons in glaucoma." (PMID 23316132, 2012). "With the use of nanoparticle-mediated gene transfer, it may be possible to have retinal ganglion and optic nerve cells produce substantial levels of BDNF to promote their own sustainability during the stress from intraocular pressure that is observed in glaucoma." (PMID 17183666, 2006). "Gene therapy has also transitioned from experimental models to clinical reality, with adeno-associated virus (AAV) vectors delivering neuroprotective genes (e.g., BDNF, CNTF) directly to RGCs in glaucoma." (PMID 40573278, 2025).